FOXA1 (forkhead box A1)
Diseases named in the same sentence as FOXA1 in open-access papers (continued):
Sharing a sentence is not in itself a finding about the gene and the disease.
breast carcinoma (continued). "In breast cancer, the TCGA study reported that 1% of the 773 breast cancer tumors tested have focal amplification of the region containing the FOXA1 genomic locus, consisting of six ER+ and two HER2 tumors." (PMID 23420418, 2013). "Another ER interacting partner, GATA3, was found to be highly mutated in all the studies (10.8% of breast cancers in TCGA study), although GATA3 and FOXA1 mutations were mutually exclusive." (PMID 23420418, 2013). "Actually, a recent study reported co-expression of ER and FOXA1 in metastatic breast cancer samples, indicating oncogenic activities of FOXA1." (PMID 23679233, 2013). "Although the precise significance of FOXA1 expression in breast cancer is unclear, FOXA1 expression has been shown as a positive prognostic factor in ERα positive tumors." (PMID 23593223, 2013). "We applied REACTIN to compare ER+ with ER- samples in ten breast cancer datasets and successful detected the activity difference of ER alpha, FOXA1 and GATA3 between ER+ and ER- breast cancer subtypes." (PMID 23885756, 2013). "Foxa1 has been shown to cooperate with the estrogen receptor (ER) in gene activation in breast cancer cell lines." (PMID 22737085, 2012). "Immunofluorescence, ChIP-seq assays and ChIP-reChIP against PBX1 and FoxA1 suggests that they co-occupy genomic regions in MCF7 breast cancer cells." (PMID 22125492, 2011). "Overall, these results reveal that PBX1 acts as a pioneer factor guiding ERα genomic activity independently of FoxA1 in breast cancer." (PMID 22125492, 2011). "A similar proportion of FoxA1 cistrome overlaps with the H3K4me2 distribution in MCF7 breast cancer cells." (PMID 22125492, 2011). "In breast cancer cells, global location analysis previously revealed that FoxA1 bound many regions located >50 Kb from a transcription start site." (PMID 20714352, 2010). "Cyclin D1 is one of the most commonly overexpressed genes in human breast cancer whose transcription is activated by FOXA-1-mediated ER-α gene regulation, as well as by β-catenin-mediated transcriptional machinery." (PMID 20565980, 2010). "Of these, the two largest (in terms of number of genes) are the estrogen set, well-documented in microarray-based studies of breast cancer, and a second set that we have labelled "FOXA1"." (PMID 20731868, 2010). "Expression profiling, by microarray DNA analysis, revealed a marked upregulation in FOXA1 in mammary carcinomas of the Wnt/ILK double-transgenic mice." (PMID 20565980, 2010). "Among those is FOXA1, which shows an average fourfold increase in expression in double-transgenic mammary tumors compared with Wnt1 tumors with > 95% confidence interval." (PMID 20565980, 2010). "In breast cancer, however, FOXA1 overexpression can also block the metastatic progression by influencing the expression of the BRCA1-associated cell-cycle inhibitor p27 and promoting E-cadherin expression." (PMID 19549328, 2009). "For example, 9-cis-Retinoic acid is recognized as a possible breast cancer biomarker and FOXA1 has gained increasing attention as a possible breast cancer therapeutic target." (PMID 19811689, 2009). "Kaplan–Meier survival curves demonstrate that patients with FOXA1-positive breast carcinomas showed a significant difference towards the longer disease-free survival time (P < 0.001)." (PMID 19549328, 2009). "The analyses showed that FOXA1 and ERα should be used together in order to subclassify breast carcinomas and to predict the outcome of breast cancer patients." (PMID 19549328, 2009). "We evaluate FOXA1 and GATA-3 expression in 249 breast carcinomas by immunohistochemistry, associating it with breast cancer molecular markers, clinicopathological features and patient's survival." (PMID 19549328, 2009).
breast carcinoma (continued). "FOXA1 was a significant predictor of good outcome in breast cancer, whereas GATA-3 was an important luminal marker." (PMID 19549328, 2009). "We demonstrated that FOXA1 expression also has an important role as breast cancer predictor of good outcome in ER-negative breast carcinomas." (PMID 19549328, 2009). "We verified that patients harbouring FOXA1-positive and ER-negative tumours show a better disease-free survival, demonstrating the clinical importance of these two biomarkers in breast cancer molecular classification and prognosis." (PMID 19549328, 2009). "The aim was to test, for the first time, the possible utility of FOXA1 and/or GATA-3 as classifiers for breast cancer recurrence in this high-risk subset of patients, revealing a stratification of ER-negative tumours with different biological behaviours." (PMID 19549328, 2009). "Previous work using immunohistochemistry has shown that the expression of FOXA1 and of GATA-3 is in close association with ERα expression in breast cancer, highlighting their prognostic and predictive value in this malignancy." (PMID 19549328, 2009). "FOXA1 and ERα have been explored as potential participants involved in mammary tumours together with another gene, GATA-3, which regulates the lineage determination and differentiation of many cells types." (PMID 19549328, 2009). "Several peer-reviewed publications have highlighted the joint regulation of the estrogen receptor-a (ESR1/ER-α), GATA3 and FOXA1 in breast cancer cells." (PMID 19104654, 2008). "Furthermore, ESR1, the gene that encodes the estrogen receptor (ER) along with pioneering transcription factor FOXA1, is well established factors in hormonally dependent breast cancer." (PMID 41363728, 2026). "Mechanistically, FOXA1 is required for nearly all ER-binding events in breast cancer cells." (PMID 40003882, 2025). "Additionally, research conducted by Y Xu and his team revealed that Twist1 can suppress FOXA1 expression, thereby enhancing the invasive and metastatic properties of breast cancer." (PMID 40003882, 2025). "The parallels between FOXA1's role in breast cancer and liver cancer suggest that targeting this gene could offer a promising approach for overcoming resistance in multiple cancer types." (PMID 40216647, 2025). "However, the molecular mechanisms through which HER2 regulates FOXA1 in ER+/HER2-low breast cancer require further investigation." (PMID 41224124, 2025). "Further studies have demonstrated that this is likely an indirect manifestation of genetic mutations characteristic of breast carcinomas/triple-negative breast cancer, leading to hyperactivation of the FOXA1 and PI3K/AKT/mTOR signaling pathways." (PMID 41155241, 2025). "However, in estrogen receptor-positive breast cancer, FOXA1 downregulation enhances sensitivity to doxorubicin and paclitaxel, while its upregulation in basal-like breast cancer cells confers increased drug resistance." (PMID 40623983, 2025). "In breast cancer, the upregulation of FOXA1 leads to the reprogramming of estrogen receptor function, contributing to endocrine resistance and the promotion of metastasis in ER-positive tumors through a High-FOXA1/ER-dependent secretory mechanism." (PMID 40623983, 2025). "We illustrated this methodology with the TF FOXA1 in breast cancer as an example." (PMID 39535029, 2025). "The actions of FOXF2 in BLBC cells are akin to those of FOXA1 in luminal breast cancer." (PMID 40003882, 2025). "Indeed, the phenotypic switch from basal-like breast cancer to luminal type can be achieved by re-expressing ERα, FOXA1 or GATA3." (PMID 41318657, 2025).
breast carcinoma (continued). "This dual-layered regulation may provide a robust mechanism to fine-tune FOXA1 activity in hormone-independent breast cancer contexts." (PMID 41224124, 2025). "Similarly, in the Invasive Breast Carcinoma (TCGA, Cell 2015) dataset, the TNBC subgroup included n = 51 samples, with FOXA1 mutations identified in only 2 cases." (PMID 41283251, 2025). "Furthermore, FOXA1’s documented role in type 2 diabetes (T2D) and its expression in breast cancer has been extensively reported in scientific literature." (PMID 39000600, 2024). "In summary, along with the observation that FOXC1 and NR2F2 co-interact, it is likely that core binding sites of FOXC1 in TNBC identified here and represented by cluster 1 and cluster 4 peaks, are sites where FOXA1/NR2F2 are bound in luminal breast cancer (and vice versa)." (PMID 39171293, 2024). "Thus, FOXA1 and FOXA2 are critical for lipid synthesis and breakdown in breast cancer, suggesting that FOXA1 and FOXA2 are potential therapeutic targets." (PMID 38605023, 2024). "Notably, elevated FOXA1 expression correlated with poorer overall survival in patients with estrogen-receptor-positive/progesterone-receptor-positive (ER+/PR+) breast cancer." (PMID 39000600, 2024). "Knockdown of FOXA1 in ER+ breast cancer reduces luminal-lineage proliferation." (PMID 39171293, 2024). "Similarly, microRNA-100 inhibited breast cancer cell proliferation, invasion, and migration by targeting FOXA1." (PMID 38605023, 2024). "Therefore, when targeting FOXA1 for treating breast cancer, we should first distinguish the type of breast cancer, detect the expression of related hormone receptors, and finally decide the treatment plan according to these conditions." (PMID 38605023, 2024). "In addition, the group found that microRNA24 (miR24) inhibited O-GlcNAc transferase to maintain FOXA1 stability and prevent breast cancer cell invasion." (PMID 38605023, 2024). "Similarly, a somatic SNV in the FOXA1 promoter region (chr14:38,064,406; G > A) has been detected in primary breast cancers." (PMID 38902506, 2024). "As for breast cancer, FOXA1 has a critical role in prostate cancer cell plasticity." (PMID 38391963, 2024). "The regulation of FOXA1-driven ER signaling may be one of the ways to control the progression of breast cancer and improve the drug resistance of breast cancer treatment." (PMID 38605023, 2024). "To check our hypothesis that FOXA1 would affect the hormone-receptor-positive breast cancer (HR+ BC) cell growth, we used CRISPR/Cas9 to knockout FOXA1." (PMID 39000600, 2024). "FOXA1 plays different roles in different breast cancer subtypes." (PMID 38605023, 2024). "Ectopic microRNA-132 expression significantly inhibited the expression of FOXA1 protein, which also inhibited the proliferation of breast cancer cells, whereas miR-132 knockdown promoted FOXA1 expression in breast cancer cells, which facilitated the proliferation of breast cancer cells." (PMID 38605023, 2024). "The role of FOXA1 in basal breast cancer is determined by ESR1 expression." (PMID 38605023, 2024). "Brown and colleagues showed that ERα binding regions are highly enriched for the FOXA1 binding motif, and subsequently, FOXA1 was identified as an important pioneer factor for ER–chromatin interactions in ER-positive breast cancer cells and as necessary for E2-mediated gene expression." (PMID 39767607, 2024). "Our study revealed that knocking down FOXA1 reduces the glycolysis level in breast cancer." (PMID 39440050, 2024). "Importantly, the balance between FOXA1 and other transcription factors determines the luminal or basal-like phenotype of breast cancer cells." (PMID 38391963, 2024). "Based on the constructed IGRN between malignant cells at the invasive front of the TME and the immune cells of ER+ breast cancer patients, we found that a high expression of the transcription factors FOXA1 and EZH2 played a key role in driving tumor progression." (PMID 38254989, 2024).
breast carcinoma (continued). "In addition to its role in ER-positive breast cancer, high levels of FOXA1 improve survival in patients with the basal breast cancer subtype." (PMID 38605023, 2024). "Here, persistent selective targeting of the ERα drives breast cancer progression towards a basal-like ERα-independent disease by depleting chromatin accessibility of ERα and pioneer factor forkhead box protein A1 (FOXA1), and reducing H3K27ac, a mark of active enhancers." (PMID 39282472, 2024). "Such therapeutic opportunities could be implemented in the treatment of FOXA1-driven, endocrine resistant breast cancer." (PMID 39282472, 2024). "Furthermore, FOXA1 deficiency was able to induce membrane-associated protein 1 (ANXA1) expression, contributing to basal breast cancer metastasis." (PMID 38605023, 2024). "Additionally, either metformin treatment or FOXA1 gene deletion enhanced tamoxifen-induced tumor growth inhibition in HR+ breast cancer cell lines within an ex vivo three-dimensional (3D) organoid model." (PMID 39000600, 2024). "Our specific focus was on FOXA1 due to its elevated expression among diabetes-related genes within the hormone-receptor-positive breast cancer (HR+ BC) subtype, as determined by gene expression analysis of breast cancer patient tissue samples." (PMID 39000600, 2024). "Furthermore, experiments demonstrated that loss of the FOXA1 gene inhibited tumor proliferation and invasion in vitro using MCF-7 and T47D HR+ breast cancer cell lines." (PMID 39000600, 2024). "In breast cancer cell lines, the FOXA1 gene is fundamentally manifested when cells express ER." (PMID 37626655, 2023). "Supporting the specificity of FOXM1 inhibitors, they did not alter the expression of FOXA1, a forkhead protein implicated in luminal breast cancers." (PMID 36795481, 2023). "Twist1 promotes breast cancer invasion and metastasis by inhibiting the expression of Foxa1." (PMID 36639679, 2023). "Notably, GRHL2 can regulate ER⍺ signaling output in hormone receptor positive breast cancer by co-occupying enhancer elements with FOXA1, GATA3, and ER⍺." (PMID 36691073, 2023). "FOXA1 plays a critical role in the regulation of ER function and may contribute to endocrine resistance in breast cancer." (PMID 37773134, 2023). "This cohort contained a subset of genes that could be considered potential biomarkers for breast cancer progression, including FOXA1, MLPH, ESR1, AR, GATA3, TFF1, THSD4, and TBC1D9." (PMID 38020889, 2023). "We speculated that the downregulation of SCUBE2 in concert with FOXA1 is part of the EMT program that plays important roles in modulating breast-cancer cell migration and invasion." (PMID 37293596, 2023). "The dependency evaluation of the cell lines with SCRIB, VANGL2 and NOS1AP amplifications with CRISPR and RNAi revealed several genes involved in breast cancer pathogenesis, such as FOXA1, ERBB2, PIK3CA and CDK4, to be among the top preferential essential genes." (PMID 36675340, 2023). "Of note, the expression of FOXA1 is low in TNBC but high in HR + breast cancer patients." (PMID 36292640, 2022). "All in all, our and others’ studies provide clear evidence for the role of FOXA1 in breast cancer and prostate cancer progression and treatment response, suggesting that the targeting of FOXA1 may be useful, in combination with standard therapy, in treatment." (PMID 36292640, 2022). "FOXA1 has been widely studied in urinary system tumors and breast cancer." (PMID 35968505, 2022). "Our gene expression/survival correlation data revealed that high co-expression of HER2, JAM-A and FOXA1 mRNA was associated with poorer survival characteristics (both distant metastasis-free survival and recurrence-free survival) in HER2-positive breast cancer patients." (PMID 35203384, 2022).
breast carcinoma (continued). "WGCNA partitioned ~20% of expressed genes into eight consensus modules that align with established hallmarks of breast cancer; for example, an ER/FOXA1-driven module expressed in luminal tumours, and a mitotic instability module in basal-like and luminal-B tumours." (PMID 35501337, 2022). "FOXA1 overexpression has been reported in luminal breast cancer and endocrine therapy resistance." (PMID 36359853, 2022). "In addition to regulating ESR1 gene expression, FOXA1 acts as a pioneer factor for AR expression not only in prostate but also in breast cancer, and, TNBCs that lose metastatic potential co-express FOXA1 and AR." (PMID 36171192, 2022). "In addition, a previous study revealed that FOXA1, which established estrogen-responsive transcriptomes, was a pioneer of nuclear receptor action in breast cancer." (PMID 36292640, 2022). "Finally, we validated our predictions in breast cancer cells and showed that FOXA1 and GATA3 indeed mediate DNA hypo-methylation." (PMID 35331302, 2022). "More importantly, the chemotherapeutic drug Etoposide, which has been shown to inhibit the growth of prostate and breast cancer, reduced FOXA1 expression in our study, concluding that FOXA1 may be useful as potential prognostic marker and therapeutic target." (PMID 36292640, 2022). "In addition, increased FOXA1 expression has been recently identified to promote cancer chemotherapy resistance in mice and patients with prostate cancer and breast cancer." (PMID 35498155, 2022). "In addition, FOXA1 expression is correlated with estrogen receptor (ER) positivity in breast cancer cell lines." (PMID 35968505, 2022). "Interestingly, we have previously found that there is positive correlation of expression between PRLR and FOXA1 in breast cancer cases." (PMID 36157462, 2022). "Data-mining results implied that FOXA1 expressed at a high level in breast carcinoma." (PMID 36292640, 2022). "FOXA1 is a pioneer transcription factor that can translate epigenetic signature into transcription regulation and also drive genome-wide enhancer reprogramming in breast cancer." (PMID 36204307, 2022). "Other studies have found that FOXA1 suppresses breast cancer cell growth and inhibits apoptosis." (PMID 35968505, 2022). "Having already established that JAM-A levels positively regulate those of the HER3 transcription factor FOXA1 in breast cancer cells, we tested whether FOXA1 levels directly altered HER2 expression in our cell lines." (PMID 35203384, 2022). "Finally, the online database kmplot.com was interrogated to examine the significance of high combined JAM-A, HER2 and FOXA1 gene expression for breast cancer patient survival." (PMID 35203384, 2022). "Nonetheless, our analysis of the ENCODE Transcription Factor ChIP-Seq dataset in the UCSC Genome Browser revealed the CXCL13-neighbor phage sequence contains an experimentally-validated consensus binding site for the transcription factor FOXA1, a key mediator of hormonal response in breast cancer." (PMID 37082114, 2022). "We next asked whether FOXA1 binds directly to AR gene sequences, promoting AR expression in breast cancer cells." (PMID 36171192, 2022). "Finally, we uncovered two possible reasons for HTR6 down-regulation in breast cancer, including deep deletion in the genome and the up-regulation of FOXA1 in breast cancer, which was a potential negatively regulatory transcription factor of HTR6." (PMID 35359970, 2022). "Since HTR6 was down-regulated in invasive breast cancer and metastases versus tumor in situ, this result suggested that FOXA1 might be the negatively regulatory TF of HTR6 in breast cancer." (PMID 35359970, 2022). "Consistently, the importance of FOXA1 in breast and prostate cancer is underlined by our results that FOXA1 is highly expressed in various prostate and breast cancers, and that FOXA1 expression at mRNA in prostate cancer is significantly higher than that in other cancer lines." (PMID 36292640, 2022).